TGFB1 (transforming growth factor beta 1)
Diseases named in the same sentence as TGFB1 in open-access papers (continued):
Sharing a sentence is not in itself a finding about the gene and the disease.
breast cancer (continued). "However, HLF was regulated by transforming growth factor-beta 1 (TGF-β1), which is ascertained as an inducer of EMT and trigger ferroptosis in isolated breast cancer cells." (PMID 39881868, 2024). "Serum levels of EGF, G-CSF, TNFα, Groα, IP10, MIP-1b, MDC, VEGFα, TGFβ1, and TGFβ2 were also high in women with breast cancer compared to the control group (no cancers)." (PMID 38541912, 2024). "The results demonstrate the capacity of TGFβ1 to orchestrate crosstalk between tumor cells and lymphatic endothelial cells and warrant further studies to explore the roles of IL7 and IL15 in promoting lymph metastasis of breast cancer." (PMID 38055067, 2023). "Indeed, the mRNA expression levels of CXCL2, TGFB1, CCL2, and IL1B were markedly increased in the breast cancer cell lines after treatment with Doxo and Abe." (PMID 37993606, 2023). "Proliferative signaling that can awaken dormant breast cancer cells may be activated through growth factors including EGF, TGFβ1, integrins, adhesion molecules and stromal remodeling." (PMID 37296983, 2023). "Since TGFβ is a crucial regulator of EMT, we then tested TGFβ signaling by qRT-PCR analysis of a panel of genes that are involved in driving breast cancer metastasis to the bone or lung in the presence or absence of TGFβ1." (PMID 35982039, 2022). "Notably, leptin has been shown to increase protein levels of TGFβ1 in ER + and ER- breast cancer cells (MCF7, MCF10AT1) and a neutralising antibody against TGFβ1 blocks leptin-mediated actions." (PMID 36038791, 2022). "Interestingly, the gene regulatory network which was activated by TGFβ1 in TKA organoids, seemingly differs from that operating in pEMT states in squamous cell carcinoma and breast cancer." (PMID 35075245, 2022). "The antitumor effect of curcumin is exerted through different molecular-signaling networks involved in proliferation, ER, HER2 pathways and the regulation of genes related to breast cancer metastasis like TGF-α, TGFβ1, SERPINE1, PGAP3, MAP3K1, MAPK1, vimentin, among others." (PMID 33572626, 2021). "The link between Smad4 and TGFβ1-dependent autophagy that we observed in NSCLC cells was consistent with studies investigating TGFβ-dependent autophagy in pancreatic ductal adenocarcinoma cell lines and breast cancer cell lines." (PMID 34760883, 2021). "Furthermore, TGFβ1 mRNA and protein levels were significantly increased by BATF overexpression and significantly reduced by BATF knockdown in breast cancer cells." (PMID 34096887, 2021). "In breast cancer cells, FOSL1 expression correlates with mesenchymal features and drives cancer stem cells and the regulation of EMT seems to happen through the direct binding of FRA-1 to promoters of EMT genes such as Tgfb1, Zeb1, and Zeb2." (PMID 34399888, 2021). "As a result, TNBC patients with liver metastasis can attract more breast cancer cells to the liver niche as they produce EVs with higher TGFβ1 levels than do healthy donors or TNBC patients without liver metastasis." (PMID 33777909, 2021). "Calycosin treatment inhibited epithelial-mesenchymal transition (EMT) of breast cancer cells by significantly increasing E-cadherin levels and decreasing N-cadherin, Vimentin, CD147, MMP-2, and MMP-9 levels through downregulation of BATF and TGFβ1." (PMID 34096887, 2021). "Moreover, the epigenetic silencing of the TGF-β gene, TGFB1, also contributes to trastuzumab resistance in Her2+ breast cancer." (PMID 33114183, 2020). "In liver cancer cells, transforming growth factor beta 1 (TGF-β1) indirectly promotes epithelial-mesenchymal transition (EMT) and CSC phenotypes through down-regulation of TP53INP1 by miR-155 while in breast cancer, miR-155 is involved in tumor initiation via transcriptional repression of BRCA1." (PMID 31137686, 2019).
breast cancer (continued). "Here, Ren and colleagues demonstrate that the TGFβ1/HOTAIR axis, by targeting CDK5 signaling, promotes the metastatic capacity of breast cancer cells, thus suggesting that its targeting may be considered a novel strategy for the treatment of breast cancer." (PMID 30927908, 2019). "We speculated that a similar mechanism is in place in breast cancer and is due to WDR5 regulation, which has a prominent role per se in EMT and metastasis, as well as through TGFβ1." (PMID 31752957, 2019). "Our results suggest that ADAMTS9 inhibits TGFβ1‐induced AKT activation, which may involve TβR(I/II) in breast cancer cells." (PMID 29193730, 2018). "In breast cancer, TGFβ1 is upregulated compared to its adjacent nonmalignant tissue and it impacts on various cells of the tumor microenvironment." (PMID 30004628, 2018). "To this end, we activated MET and TGFβ signaling pathways with HGF and TGFβ1, respectively, and tested their influence on TGFBR2 or MET expression in the model cell line MCF10A as well as in basal‐like breast cancer cell lines HS578T and HCC1143." (PMID 30004628, 2018). "TGFB1, TNF, IL1B and IL6 are inhibited by ligand-bound AhR in ERα-positive breast cancer cells." (PMID 29320557, 2018). "By revealing TGFβ1 as a regulator of HGF/MET‐induced cell migration, our findings suggest TGFβ1 with its downstream mediators C‐ets‐1 and miR‐128‐3p as potential targets for therapy of basal‐like breast cancer." (PMID 30004628, 2018). "Indeed, TGFβ1‐induced expression of ETS1 and breast cancer cell migration was blocked by knockdown of ETS1." (PMID 30004628, 2018). "Nevertheless, the exact mechanisms of TGFβ1/TGFBR2‐driven breast cancer progression and metastasis have not been fully elucidated until now." (PMID 30004628, 2018). "As SP1 is involved in TGFβ1‐induced MET expression in renal epithelial cells, MET might be also regulated by miR‐128‐3p via SP1 in breast cancer." (PMID 30004628, 2018). "The TGF– β family is involved in most of the considered diseases, e.g., TGFB1 in Osteoporosis, TGFB3 in Rheumatoid arthritis, Osteoarthritis and Multiple myeloma, TGFBR2 in HIV, Osteomyelitis and Measles, BMP in Breast cancer and Osteosarcoma, and BMP3 in Periodontitis." (PMID 30497370, 2018). "However, this trend was reversed for plasma VEGF and TGFβ1 since the early onset breast cancer patients had higher mean plasma VEGF and TGFβ1 compared to older patients." (PMID 28607365, 2017). "Contrary to observations in the plasma, a majority of the studied PBMC genes PlGF, VEGF, TGFβ1, PLXNA1 and VEGFR3, indicated similar expression in both early onset and older breast cancer patients, with controls showing higher variability between the two age groups." (PMID 28607365, 2017). "Having validated the use of the Z-cad dual sensor system to detect EMT/MET in claudin-low breast cancer cells expressing inducible miR-200c, we next asked if we could identify cells with EMT/MET properties using the Z-cad dual sensor in response to TGFβ1." (PMID 27317311, 2016). "Besides, the prognostic significance of the TGFβ1, SMAD4 in breast cancer patients is an area of many contradictions." (PMID 26040677, 2015). "Sadej and colleagues showed that CD151 is required for TGFβ1-induced proliferation and scattering of breast cancer cell line MDA-MB-231 through regulating TGFβ-induced p38 phosphorylation, rather than canonical TGFβ-induced Smad phosphorylation." (PMID 25978409, 2015). "Protease inhibition did not affect invasion of TGFβ-1 treated normal mammary epithelial cells, but reduced the invasion of murine breast cancer cells." (PMID 25744631, 2015). "Our study aims to define the prognostic significance of TGFβ1, SMAD4 and TIF1γ expression in breast cancer patients and to detect possible interactions among those markers that might affect the outcome." (PMID 26040677, 2015).
breast cancer (continued). "Transforming growth factor β1 (TGFβ1) is believed to promote tumor development and metastasis through epithelial to mesenchymal transition (EMT), a process that enables epithelial cells migrate to distant areas during late stages of breast cancer development." (PMID 25874926, 2015). "Therefore we inhibited cathepsins in TGFβ-1 treated normal murine mammary gland epithelial cells (NMuMG) and cells derived from late stage tumors of the murine MMTV-PyMT breast cancer model." (PMID 25744631, 2015). "We investigated the association between 89 single nucleotide polymorphisms (SNPs) in 7 cytokine/growth-factor genes (FGFR2, IGFBP1, IGFBP3, TGFB1, TNF, VEGF, IL6) and percent MD in 301 premenopausal women (aged 50 to 55 years) participating in the Norwegian Breast Cancer Screening Program." (PMID 23762340, 2013). "We examined whether murine breast cancer 4T1 cells, which showed EMT upon treatment with TGFβ1 or doxorubicin, could exhibit stem cell characteristics in vitro." (PMID 20442777, 2010). "However, slightly lower levels of TGFβ1 (P<0.0001) and MMP-2 (P=0.03) and a small increase of MMP-9 (P=0.001), OPG (P=0.003) and CTX (P=0.0007) have been detected in breast carcinoma patients." (PMID 16880790, 2006). "To identify chemotactic factors induced in SV-LECs by TGFβ1 that could stimulate chemotaxis of breast cancer cells with mesenchymal properties we performed RNA sequencing and differential gene expression analysis of TGFβ1-treated versus non-treated SV-LECs." (PMID 38055067, 2023). "Direct contact between platelets and MCF-7 through integrin α2β1 has also been observed in breast cancer, which not only activates the Wnt-β-catenin pathway and promotes the expression of EMT-related proteins, but also synergistically facilitates EMT by inducing the TGFβ1 autocrine from tumor cells." (PMID 35659308, 2022). "TGFβ1 and TGFβ2 are potent upstream regulators of Blimp1 in dermal fibroblasts and may potentially act via the c-RAF to AP-1 pathway identified in breast cancer cells." (PMID 28668474, 2017). "Indeed in our study, we also observed a significant interaction between TGFβ1, TIF1γ expression and the prognosis of breast cancer patients, an interaction that was not investigated in previous studies." (PMID 26040677, 2015). "By applying quantitative proteomics and cell biological approaches we show that lysosomal protease inhibition results in accumulation of lysosomes and lysosome-related proteins thereby significantly reducing invasion of TGFβ-1 treated breast cancer cells but not of normal mammary epithelial cells." (PMID 25744631, 2015). "Our study investigated for the first time the serum levels of TGFβ1 in patients with and without bone metastasis and identified that both breast cancer patients with and without bone metastases had significantly lower levels compared to healthy age-matched controls." (PMID 16880790, 2006). "On the other hand, virally transformed tumorigenic mammary epithelial cell lines as well as most of the cell lines derived from invasive human breast carcinomas are resistant to the antiproliferative effects of TGFβ1 in vitro and do not respond to treatment with TGFβ1 in vivo." (PMID 16404434, 2006). "Furthermore, scRNA-seq of breast cancer indicated that the angiogenesis factors plasminogen activator, urokinase receptor (PLAUR) and IL-8 were expressed in TAMs in addition to M2-type genes, such as CD163, membrane spanning 4-domains A6A (MS4A6A), and transforming growth factor beta-1 (TGF-β1)." (PMID 36154923, 2022). "TGFβ1 is expressed by bone myeloid cells, is the predominant TGFβ isoform in bone, and is released from bone matrix stores into the bone microenvironment during osteolysis, an event that dominates in the majority of breast cancer BMETs, regardless of the tumor subtype." (PMID 33923316, 2021).
breast cancer (continued). "Thus, while maternal obesity does not increase FOXP3 levels in the offspring’s mammary tumors, upregulation of Tgfβ1 and VEGFR2 suggests that maternal HFD may promote immunosuppression in TAM-treated offspring’s mammary tumors." (PMID 32580156, 2020). "While it is established that transforming growth factor beta-1 (TGF-β1) can induce EMT, the effect of cytokine-induced EMT on O-glycosylation of breast cancer cells has not previously been explored." (PMID 41764140, 2026). "We observed interactions of TGFB1 and IGFBP‐3 gene expression with a family history of breast cancer (data not shown)." (PMID 35304837, 2022). "Subsequent validation analyses by qPCR revealed a strong down-regulation of TGFB1 mRNA levels in response to increased Rab31 expression not only in CAMA-1 cells, but also in another breast cancer cell line, MDA-MB-231." (PMID 34906074, 2021). "Several of the immune genes were expressed at a significantly lower level in the resistant than sensitive mammary tumors in the HFD offspring not treated with genistein: Foxp3 (p = 0.012), Tgfb1 (p < 0.001), Ctla4 (p = 0.023) and Il6 (p = 0.018)." (PMID 33440675, 2021). "However, the IL7R and the IL15Ra were not induced during TGFβ1-induced EMT in NMuMG cells, suggesting that other signaling pathways drive the expression of these receptors in basal breast cancer cells." (PMID 38055067, 2023). "Gene clusters correlating positively (including known GRHL2 targets such as ErbB3, CLDN4/7) or negatively (including TGFB1 and TGFBR2) with GRHL2 in the MCF7 knockout model, display similar correlation with GRHL2 in ER positive as well as ER negative breast cancer patients." (PMID 36691073, 2023). "We could also conclude that the value of TGFβ1, SMAD4 and TIF1γ expression in breast cancer should not be considered individually but instead combined to serve as an effective prognostic tool for breast cancer." (PMID 26040677, 2015). "Based on the role of TGFB1 (inhibition of proliferation) and WNT4 (induction of proliferation) in non-cancer tissues, these influences could result in less proliferation of breast epithelium in women without breast cancer." (PMID 34921608, 2022). "In conclusion, we have identified that TGFβ1 regulates HGF‐induced and MET‐mediated cell migration, through positive regulation of C‐ets‐1 and negative regulation of miR‐128‐3p expression in basal‐like breast cancer cell lines and in triple‐negative breast cancer tissue." (PMID 30004628, 2018).
pulmonary fibrosis (2,456 papers, 1996 to 2026). Chronic progressive interstitial lung disorder characterized by the replacement of the lung tissue by connective tissue, leading to progressive dyspnea, respiratory failure, or right heart failure. "In conclusion, our findings emphasize the elevated mitochondrial ROS levels in bleomycin-induced pulmonary fibrosis, along with the upregulation of Tgfb1-centered oxidative stress-associated fibrosis genes." (PMID 40978478, 2025). "Regarding their predominant role in the immune system, TGFB1 has been linked to pulmonary fibrosis in COVID-19 patients." (PMID 38731851, 2024). "Myofibroblast transition and ECM overproduction are known to be induced by several profibrotic mediators, including transforming growth factor-β1 (TGFβ1), which is the most critical profibrotic factor, and its excessive secretion can cause lung fibrosis." (PMID 37047142, 2023). "Various autophagy genes, including P62, ATG5, ATG7, ATG16l1 or ULK2, are associated with the regulation of TGFβ1 in lung fibrosis, but little is known about the role of TGFβ1 in the modulation of autophagy in IBD." (PMID 37397491, 2023). "In the present study, we found that treatment with a neutralizing anticorisin mAtb improves abnormal radiological findings and lung inflammation induced by corisin in a mouse model of TGFβ1-associated lung fibrosis." (PMID 35322016, 2022). "M2 macrophages contribute to pulmonary fibrosis by releasing TGFβ1 and PDGF, which, in turn, cause fibroblasts to differentiate into myofibroblasts which mediate fibrosis." (PMID 35401519, 2022). "In the context of lung fibrosis, hedgehog signaling has also been implicated in the control of TGFβ1-dependent myofibroblast differentiation in patients with Idiopathic Pulmonary Fibrosis (IPF)." (PMID 36230980, 2022). "We have previously established a novel mouse model of lung fibrosis based on Adeno-associated virus (AAV)-mediated pulmonary overexpression of TGFβ1." (PMID 35842487, 2022). "We measured the plasma levels of corisin in wild-type (WT) mice and TGFβ1 transgenic mice (TG) with pulmonary fibrosis caused by lung-specific overexpression of the full-length human TGFβ1 encoding gene and evaluated correlation with fibrosis markers." (PMID 35322016, 2022). "It was demonstrated that NOX4 deficiency or acute treatment with a NOX4 inhibitor blunted TGFβ1-induced alveolar epithelial cell death and prevented subsequent pulmonary fibrosis in a murine model of lung fibrosis." (PMID 35662702, 2022). "Another limitation of the present study is that the comparison of PFD therapeutic efficacy between the oral and intranasal drug delivery was performed only in the TGFβ1-associated lung fibrosis model." (PMID 33390975, 2020). "In contrast, rats treated with an adenovirus encoding active TGFβ1 developed extensive pulmonary fibrosis associated with increased expression of αvβ6 integrins within the alveolar epithelium." (PMID 27494713, 2016). "In fact, recent studies in PINK1 null mice demonstrated high levels of TGFβ1 and susceptibility to pulmonary fibrosis." (PMID 26059457, 2015). "Here, TGFβ1 was found to be predictively associated with the functional clusters ‘invasion of cell’, ‘idiopathic pulmonary fibrosis (IPF)’, and ‘metastasis’." (PMID 26243655, 2015). "It is well known that a higher TGFβ1 production and a high-producer TGFβ1 genotype are associated with the development of increased lung fibrosis." (PMID 24062613, 2013). "In idiopathic pulmonary fibrosis, the lung epithelium plays a key role in the fibrotic response and integrin-mediated activation of TGFβ1 has been implicated as a primary driver of this pathophysiology." (PMID 23547562, 2013). "Using an oligonucleotide microarray based strategy we identified discrete patterns of gene expression contributing to TGFβ1 associated pulmonary fibrosis." (PMID 17883846, 2007).